RCOR1 (REST corepressor 1)
Description:
Essential component of the BHC complex, a corepressor complex that represses transcription of neuron-specific genes in non-neuronal cells. The BHC complex is recruited at RE1/NRSE sites by REST and acts by deacetylating and demethylating specific sites on histones, thereby acting as a chromatin modifier. Plays a central role in demethylation of Lys-4 of histone H3 by promoting demethylase activity of KDM1A on core histones and nucleosomal substrates. It also protects KDM1A from the proteasome. Component of a RCOR/GFI/KDM1A/HDAC complex that suppresses, via histone deacetylase (HDAC) recruitment, a number of genes implicated in multilineage blood cell development and controls hematopoietic differentiation.
Synonyms: KIAA0071; RCOR; COREST
Tractability: Small molecule: a structure with a bound ligand is known; a high-quality ligand is known. PROTAC: UniProt records ubiquitination sites on it; ubiquitination databases record sites on it; its protein half-life has been measured; a small molecule that binds it is known.
Gene: Protein-coding gene on chromosome 14 (102,592,649 to 102,730,576, forward strand). Ensembl gene ENSG00000089902.
Subcellular location: Nucleus
Subcellular location (Human Protein Atlas): Nucleoplasm
Pathways (Reactome):
Chromatin organization: HDACs deacetylate histones
Disease: Potential therapeutics for SARS
Hemostasis: Factors involved in megakaryocyte development and platelet production
Signal Transduction: Regulation of PTEN gene transcription
Gene Ontology:
Molecular function: protein binding; transcription corepressor activity; chromatin binding; enzyme binding
Biological process: negative regulation of DNA-templated transcription; regulation of transcription by RNA polymerase II; erythrocyte differentiation; negative regulation of gene expression; positive regulation of megakaryocyte differentiation
Cellular component: DNA repair complex; histone methyltransferase complex; nucleoplasm; nucleus; transcription repressor complex; histone deacetylase complex; transcription regulator complex
Genetic constraint (gnomAD): Loss-of-function variants: 9 observed, 23.32 expected, observed/expected ratio (o/e) 0.39, 90% interval 0.23 to 0.67. The synonymous counts are far from expectation, so gnomAD's model fits this gene poorly and the ratio says little. Missense variants: 317 observed, 328.29 expected, observed/expected ratio (o/e) 0.97, 90% interval 0.88 to 1.06. Synonymous variants: 182 observed, 129.65 expected, observed/expected ratio (o/e) 1.4, 90% interval 1.24 to 1.59.
Homologues: Orthologues: chimpanzee RCOR1 (99% identical), macaque RCOR1 (97% identical), dog RCOR1 (95% identical), mouse Rcor1 (92% identical), rat Rcor1 (92% identical), pig RCOR1 (87% identical), guinea pig RCOR1 (86% identical), tropical clawed frog rcor1 (74% identical), rabbit RCOR1 (68% identical), zebrafish rcor1 (65% identical), Drosophila melanogaster CG16779 (31% identical), Caenorhabditis elegans F28F8.7 (10% identical), and 4 more. Paralogues in human: RCOR3 (56% identical), RCOR2 (48% identical), MIDEAS (16% identical), ZNF541 (15% identical), TRERF1 (14% identical).
Diseases named in the same sentence as RCOR1 in open-access papers:
RCOR1 is named in the same sentence as 59 diseases in open-access papers, as found by Europe PMC text mining. Sharing a sentence is not in itself a finding about the gene and the disease. The quoted sentences say what the papers report.
breast carcinoma (13 papers, 2017 to 2025). "Compared with the control normal groups, RCOR1 displays different expression level among oral squamous cell carcinoma, prostate cancer, breast cancer, ovarian cancer, lymphoma, glioma patients." (PMID 37342230, 2023). "RCOR1 activates the secretion of angiogenic and inflammatory factors, strengthening tumor-induced angiogenesis and inflammatory responses in breast cancer." (PMID 37342230, 2023). "Most RCOR1- and MYC-binding motifs were located within a span of a nucleosome length of DNA (approximately 180 bp), which was also true in two different types of cancer cell lines: lymphoblast (K562) and breast cancer (MCF7)." (PMID 41227344, 2025).
melanoma (7 papers, 2018 to 2025). A malignant, usually aggressive tumor composed of atypical, neoplastic melanocytes. "Among the genes notably downregulated across all three RCOR1-KD melanoma cell lines, we noted several core components of key RNA processing complexes." (PMID 41227344, 2025). "In TCGA data sets, we observed that NOLC1 was among the top genes correlated with RCOR1 expression both in pan-cancer and melanoma patient cohorts." (PMID 41227344, 2025). "In this study, we observed that post-transcriptional RNA processing genes are downregulated with the depletion of RCOR1 in melanoma cell lines, with significant changes in the alternative splicing patterns." (PMID 41227344, 2025). "To further investigate the regulation of NOLC1 by the CoREST complex, we depleted RCOR1 by shRNA in four melanoma cell lines." (PMID 41227344, 2025). "The expression levels of RCOR1 show a significant correlation with a subset of RNA processing genes regulated by the CoREST complex in cancer patients, including melanoma." (PMID 41227344, 2025). "TCGA data were further analyzed to explore the relationship between DUSP1 and RCOR1 expression in 412 melanoma specimens from patients." (PMID 38300709, 2024). "To gain insights into the functional roles of the CoREST complex in cancer cells, we knocked down RCOR1 by shRNA in three melanoma cell lines (A375, WM983B, and SK-MEL2) and confirmed the downregulation by RT-PCR and Western blot followed by transcriptomic analysis by RNA-sequencing." (PMID 41227344, 2025). "In addition, silencing of the CoREST scaffolding protein RCOR1 also led to resensitization of BRAFi-R MITFhi/AXLlo and MITFlo/AXLhi melanoma cells to PLX4032." (PMID 38300709, 2024). "We then compared the protein level of NOLC1 with RCOR1 and MYC in a panel of fourteen melanoma cell lines." (PMID 41227344, 2025). "To explore the possibility of the CoREST complex and MYC cooperatively playing a regulatory role in the transcriptional activation of RNA processing genes, we performed RCOR1 and MYC chromatin immunoprecipitation sequencing (ChIP-seq) for both RCOR1 and MYC in A375 melanoma cells." (PMID 41227344, 2025).
glioblastoma (4 papers, 2009 to 2024). The most malignant astrocytic tumor (WHO grade IV). "Upregulation of RCOR1 may maintain the tumor stem-like phenotype in diffuse astrocytoma (DA), anaplastic oligodendroglioma (AO), and glioblastoma multiforme (GBM)." (PMID 37342230, 2023). "RCOR1 may cause deregulated expression of SYN1, which contributes to the maintenance of glioblastoma stem-like cells (GSC)." (PMID 32328342, 2020).
glioma (4 papers, 2009 to 2022). A benign or malignant brain and spinal cord tumor that arises from glial cells (astrocytes, oligodendrocytes, ependymal cells). "The prognostic effect of RCOR1 has been elucidated across cancer types, including glioma, and diffuse large B-cell lymphoma, although the prognostic effect of RCOR1 is still vague in bladder cancer." (PMID 28977887, 2017).
acute myeloid leukemia (3 papers, 2019 to 2023). Acute myeloid leukemia (AML) is a group of neoplasms arising from precursor cells committed to the myeloid cell-line differentiation. "The N-terminal SNAG domain of the transcriptional repressor GFI1 binds to the CoREST transcriptional complex proteins LSD1 and RCOR1 at the enhancers of transcription factor genes, such as SPI1 (PU.1), CEBPA and IRF8 which are important for acute myeloid leukemia cell differentiation." (PMID 38135679, 2023). "In the referred model of retinoic acid-induced differentiation of acute myeloid leukemia cells LSD1 played a scaffolding role, and LSD1 inhibition impeded the interaction between LSD1 and GFI1, but not with HDAC1/2 and RCOR1." (PMID 34572113, 2021).
colon cancer (3 papers, 2018 to 2025). "Confocal microscopy results also revealed the binding between HKDC1 and RCOR1 in colon cancer cells." (PMID 40209953, 2025). "Through colocalization and immunoprecipitation (IP) experiments, we demonstrated the interaction between HKDC1 and RCOR1 in colon cancer cells." (PMID 40209953, 2025).
gout (3 papers, 2025). A condition characterized by painful swelling of the joints, which is caused by deposition of urate crystals. "These evidences suggest that the RCOR1 site possesses pro-inflammatory activity, and facilitates the progression from hyperuricemia to gout." (PMID 40826728, 2025). "Whole-genome sequencing studies further identify novel genetic loci (RCOR1, FSTL5-MIR4454) and transporter variants (ABCG2, SLC22A12) associated with early-onset gout, with RCOR1 promoting NLRP3 inflammasome activation and IL-1β release, which are key drivers of gouty inflammation." (PMID 40880930, 2025).
depression (2 papers, 2017 to 2023). "These protein targets, especially hubs, and the functional nodes, MTOR, CDK6, SHC1, RCOR1 CCNA2 and STAT3, have been already reported to be involved in depression." (PMID 28954415, 2017). "While its direct involvement in the development of depression or BC is not known, this SNP interacts with several genes that have already been reported (i.e., TRAF3 and RCOR1), or that could play a role in the pathogenesis of the two traits (i.e., AMN, ANKRD9, and MIR4309)." (PMID 37143087, 2023).
neuroblastoma (2 papers, 2015 to 2016). Neuroblastoma (NB) is the most common solid, extracranial childhood tumor.
Tinnitus (2 papers, 2021). Tinnitus is an auditory perception that can be described as the experience of sound, in the ear or in the head, in the absence of external acoustic stimulation. "One SNP (rs4906228) upstream of the RCOR1 gene showed genome-wide significant association with tinnitus (P = 1.7 × 108)." (PMID 34482816, 2021). "We examined whether there was evidence that the association of RCOR1 with tinnitus might be secondary to its effect on hearing by analysing any association with self-reported hearing difficulty in the UKBB cohort previous GWAS22." (PMID 33742053, 2021). "This suggests that there are distinct regulatory mechanisms and requirements for the RCOR1-REST repressor complex in both hair cells of the inner ear and neurons of the brain, both potential pathogenic sites for a tinnitus phenotype." (PMID 33742053, 2021).
diabetes (1 paper, 2022). "CD36, a fatty acid transporter, was previously shown to be associated with diabetes, while the role of LAPTM4B and RCOR1, significantly dysregulated in δ-cells, remains unclear and requires further investigation." (PMID 35885959, 2022).
hearing loss (1 paper, 2021). "Furthermore, examination of the individual locus plot for rs4906228 upstream of RCOR1 in the hearing difficulty UKBB GWAS shows little evidence of an association with hearing loss suggesting this association is not purely a secondary effect of an association with hearing loss." (PMID 33742053, 2021).
hepatocellular carcinoma (1 paper, 2025). A malignant tumor that arises from hepatocytes. "In hepatocellular carcinoma, KRT19 enhances the interaction of histone deacetylase 1 and REST corepressor 1 to increase the deacetylase activity of the corepressor of RE-1 silencing transcription factor (CoREST) complex, resulting in dedifferentiation and tumorigenesis." (PMID 41345704, 2025).
renal carcinoma (1 paper, 2017). A carcinoma arising from the epithelium of the renal parenchyma or the renal pelvis. "Out of the unique set of genes detected by BNNPT, a few were reported to be relevant to renal cancer or disease: CDCP1, GSTT1, E2F3, MAPK1, SALL4, SIRT1, ADAMTS13, Gfrα1, ASPH, MIR17HG, APOE, BMP4, RCOR1, NUMB and SEC63." (PMID 28986523, 2017).
cancer (36 papers, 2009 to 2025). A tumor composed of atypical neoplastic, often pleomorphic cells that invade other tissues. "Although RCOR1 has been implicated in tumorigenesis across various cancers, its role in CRC remains unexplored." (PMID 40209953, 2025). "By interacting with REST and other cofactors, RCOR1 modulates chromatin structure to inhibit gene transcription, playing a vital role in processes such as neurodevelopment, cellular differentiation, and cancer progression." (PMID 40209953, 2025). "A very similar pattern was observed in the TCGA pan-cancer data set, where NOLC1 was one of the top two genes positively correlated with RCOR1 expression." (PMID 41227344, 2025).
tumor (26 papers, 2013 to 2025). "RCOR1 overexpression counteracted the suppression of CRC cell proliferation and migration caused by HKDC1 knockdown, while RCOR1 knockdown inhibited the tumor-promoting effects of HKDC1 overexpression." (PMID 40209953, 2025). "Comparing the expression of the CDDP-DTP-associated genes between tumor and normal adjacent tissue, and its clinical relevance, we found that six (GADD45A, SOCS1, EPS15, GLI3, NR2F2, and RCOR1) of the hub genes have significant differences." (PMID 37916165, 2023). "In contrast, the expressions of SOCS1, EPS15, GLI3, NR2F2, and RCOR1 were significantly decreased in tumor compared to normal tissue (p < 0.05)." (PMID 37916165, 2023). "Studies have shown an elevated expression of components of the CoREST complex, such as RCOR1 and LSD1, in various tumor cells compared with normal cells." (PMID 41227344, 2025). "Overexpression of RCOR1 significantly reversed the inhibitory effects of HKDC1 knockdown on CRC proliferation and migration, while silencing RCOR1 mitigated HKDC1's pro-tumor effects." (PMID 40209953, 2025). "This study showed that Foxp3 is physically associated with Rcor1, Rcor2, and Lsd1 and that depletion of Rcor1 in Foxp3+ cells leads to enhanced expression of IL-2 and IFN-γ, which provides increased anti-tumor CTL responses." (PMID 34943965, 2021). "GSCALite analysis showed that each member of RCORs exhibited different activation or inhibition in common signaling pathways, indicating that RCOR1, RCOR2, RCOR3 probably work independently or competitively in tumor progression so that leading to opposite effect on the prognosis of cancer patients." (PMID 37342230, 2023). "To detect the expression of RCOR1 in HCC tissue, we performed IHC staining of HCC tissue microarrays, indicating that RCOR1 protein was located in both nucleus and cytoplasm, and RCOR1 protein level was higher in tumor specimens than in matched adjacent non-tumor tissues." (PMID 37342230, 2023). "RCOR1 and RCOR2 expression differed significantly among tumor stages, whereas no significance exists between RCOR3 expression and tumor stages, we still noticed that RCOR3 expression elevated progressively among stage II, III, and IV." (PMID 37342230, 2023).
RCOR1 also shares sentences with these, for which no sentence is quoted: infection (7 papers); ischemia (4); leukemia (4); neurodegenerative disease (4); Merkel cell carcinoma (3); Stroke (3); Alzheimer disease (2); breast tumor (2); colorectal cancer (2); Huntington disease (2); ischemic stroke (2); Rett syndrome (2); triple-negative breast carcinoma (2); Aicardi–Goutières Syndrome (1); Alpha-thalassemia (1); atherosclerosis (1); bladder cancer (1); Cerebral ischemia (1); diffuse large B-cell lymphoma (1); endometriosis (1); ependymoma (1); frontotemporal dementia (1); gastric cancer (1); hematologic cancers (1); hematologic malignancies (1); hyperuricemia (1); latent infection (1); lymphoma (1); medulloblastoma (1); memory impairment (1).
A further 13 diseases each share a sentence with RCOR1 in 1 paper.